ISG15 (ISG15 ubiquitin like modifier)
Diseases named in the same sentence as ISG15 in open-access papers (continued):
Sharing a sentence is not in itself a finding about the gene and the disease.
bacterial infections (38 papers, 2011 to 2025). "ISG15 has been implicated in various biomarker panels for differentiating viral and bacterial infections." (PMID 39861921, 2025). "Gene Set Enrichment Analysis indicated that bacterial infection was associated with upregulation of IFNβ, ISG15, and IL10." (PMID 37876725, 2023). "This study demonstrated that children carrying a genetic mutation in the ISG15 gene were highly susceptible to intracellular bacterial infections." (PMID 35159348, 2022). "ISG15 can be induced by various pathogenic stimuli such as viral and bacterial infections, lipopolysaccharide (LPS), retinoic acid, or certain genotoxic stressors." (PMID 32969837, 2020). "Mice deficient in Isg15 (Isg15-/-) are more susceptible to infections with several viral and bacterial infections." (PMID 30818341, 2019). "ISG15 contributes to host resistance to viral and bacterial infections, either by covalent modification of target proteins, or as a secreted cytokine associated with IFN-γ responses." (PMID 40627782, 2025). "The function of ISG15 during viral infection has been extensively studied, but its role in bacterial infection, particularly intracellular bacteria, is less clear." (PMID 40627782, 2025). "In summary, the conjugation of ISG15 is a crucial defense mechanism of our immune system to combat viral and bacterial infections, and an important mediator of interferon signaling." (PMID 40631552, 2025). "We thus tested the possibility that Chlamydia-induced ISG15 was secreted extracellularly and controlled the expression of proinflammatory cytokines by HeLa cells upon bacterial infection from this location." (PMID 39345209, 2024). "Intracellular ISG15 and ISGylation have been extensively studied in the context of viral and bacterial infections." (PMID 37025175, 2023). "Bacterial infection significantly upregulated mRNA expression levels of Isg15, Mx1, Mx2, Irf-3, Irf-7, Tlr-2, Tnf-α, Cxcl-1, and Il-6 genes." (PMID 37929187, 2023). "ISG15 can be induced by multiple factors, including viral and bacterial infections, lipopolysaccharide, retinoic acid, or specific genotoxic stressors." (PMID 36465909, 2022). "IFN-γ production is crucial to fighting intracellular bacterial infections, and purified free ISG15 was previously shown to activate human NK cells and induce secretion of IFN-γ in vitro." (PMID 35159348, 2022). "ISG15 also plays a dual role in combating bacterial infections." (PMID 40103488, 2025). "Additionally, a 10-gene panel, also featuring ISG15, can differentiate viral from bacterial infections with an AUC of 0.97, with a sensitivity of 0.93 and a specificity of 0.97." (PMID 39861921, 2025). "Despite its similarities to ubiquitin, ISG15's biological function is still poorly understood; however, ISG15 appears to play important roles in various biological and cellular functions, including innate immunity, anti-viral/bacterial infections, protein turnover, and tumorigenesis." (PMID 39113797, 2024). "Notably, ISG15 plays critical roles in regulating the type I interferon response and modulating host immunity to both viral and bacterial infections." (PMID 37293015, 2023). "Notably, the ubiquitin-like protein ISG15 was necessary for increased GML levels induced by bacterial infection, and enhanced ISG15 conjugation correlated with GML levels following serum starvation." (PMID 37954520, 2023). "ISG15 is a ubiquitin-like modifier that can be upregulated in response to bacterial infections." (PMID 31772204, 2019). "The role of ISG15 during bacterial infection remains elusive." (PMID 26259872, 2015). "The role of one particular ISG, ISG15, during bacterial infection remains elusive." (PMID 26259872, 2015). "ISG15 is typically expressed at low levels under physiological conditions but is one of the most highly expressed ISGs when activated by type I interferons (IFN-Is), lipopolysaccharide (LPS), DNA damage, viral and bacterial infections, or other pathogenic stimuli." (PMID 40103488, 2025).
bacterial infections (continued). "This is particularly interesting since ISG15-driven metabolic reprogramming may explain many of the phenotypes observed during stress conditions, including those generated during either viral or bacterial infections." (PMID 36416643, 2022). "Using this comparative approach, we were able to map 930 ISG15 sites on 434 proteins in the liver of mice infected with L. monocytogenes, the first study reporting on the proteome-wide identification of ISG15 modification sites, directly in an in vivo model of bacterial infection." (PMID 34447387, 2021). "In vivo ISGylome studies in murine models following bacterial infection has revealed several proteins such as mTOR, WIPI2, AMBRA1 and RAB7 that are ISG15 modified, resulting in increased autophagy." (PMID 36416643, 2022). "ISG15 is an ubiquitin-like modifier that is transcriptionally induced by type I and III IFNs, viral and bacterial infections." (PMID 35062278, 2021). "Isg15, an IFN-induced ubiquitin-like protein, upregulated and largely binds to target protein during bacterial infection to function via the JAK-STAT pathway." (PMID 33330617, 2020). "Still, several differentially expressed genes identified in our study overlapped with those frequently appearing in other published signatures differentiating bacterial from non-bacterial infections developed in immunocompetent children, including IFI27, OASL, and ISG15." (PMID 40806258, 2025). "Interferon-stimulated gene 15 (ISG15), a ubiquitin-like protein and an amplifier of inflammation, can be induced by interferon (IFN), viral and bacterial infections, or certain genotoxic stressors, indicating that the expression of ISG15 represents a host response to pathogenic insults." (PMID 39589832, 2025). "The increase in ISG15 level upon another bacterial infection, Listeria monocytogenes, was also independent of IFN-I." (PMID 39345209, 2024). "Moreover, GSEA identified IFNAR1, ISG15 and IL10 as potential regulators of both bacterial infection and immune response." (PMID 37876725, 2023). "While this model contributes to our understanding of the antiviral activity of ISG15, it does not explain how ISGylation counteracts bacterial infections." (PMID 34447387, 2021). "We found three genes, namely BATF, ISG15 and DNMT1, which can distinguish viral from bacterial infections in a wide range of cohorts including different pathogens, ages and populations, and with potential to become clinical biomarkers for infectious diseases in a clinical setting." (PMID 33808774, 2021). "In addition, a further 12 ISGs of 380 tested ISGs including STAT1, STAT2, JAK1, IRF9, IRF2, IRF7 are key elements of IFN signaling, and classical and well-known ISGs such as ISG15, PKR, MX1, IFIT1, PML, IFI27 play key roles in viral or bacterial infections." (PMID 30717477, 2019). "Chlamydia trachomatis is an interesting infectious bacterium to further explore the role of ISG15 in the innate host response to bacterial infection, since it is a Gram-negative bacterium that develops in a different cell type than Mycobacterium, and in a vacuole, unlike Listeria." (PMID 39345209, 2024). "Notably, both ISG15 and IL10 play a crucial role in the innate immune response to viral or microbial infections, and the ISG15/IL-10 axis has been shown to exert an anti-inflammatory effect in bacterial infections as well." (PMID 37876725, 2023). "However, it is not clear what role ISG15 plays in fighting bacterial infections." (PMID 26259872, 2015).
infectious disease (12 papers, 2015 to 2026). A disorder directly resulting from the presence and activity of a microbial, viral, or parasitic agent in humans. "The “infectious disease: viral” pathway involving ISG15 was also enriched at both omics levels, with the ISG15 protein significantly upregulated." (PMID 41311493, 2025). "The immune/inflammatory response and infectious disease network showed 32 mRNAs and 17 proteins with altered expression, with key proteins such as ISG15, OAS1A, and RIG-1." (PMID 40700094, 2025). "In a further example, three Chinese siblings with intracranial calcifications and epileptic seizures, without severe infectious diseases, were exome sequenced and a mutation in ISG15 was identified." (PMID 29230214, 2017). "Overrepresentation analyses of upregulated proteins yielded six Reactome pathways enriched, highlighting “HSA-5663205: Infectious disease” (strength = 1.19; FDR = 0.003), which included the proteins RPL18A, PSMA5, HSPA1B, RPL35A, and ISG15." (PMID 39409176, 2024). "Notably, this high expression was the case for Il-1ß, ISG15, and CASP4, which are crucial for infectious diseases." (PMID 26159724, 2015). "And sixteen genes of ‘Antimicrobial Response, Infectious Diseases and Inflammatory Response’ as the top network of RSK2 KO-specific DEGs were shown to have three DEGs highly correlated with RSK2 expression with significant R and p values (ISG15, LYN and STAT5B)." (PMID 36684450, 2022).
neurodegenerative disease (8 papers, 2020 to 2024). A disorder of the central nervous system characterized by gradual and progressive loss of neural tissue and neurologic function. "On the other hand, a possible preventive approach to neurodegenerative diseases by suppression of ISG15 needs attentions because ISG15-deficient patients are susceptible to mycobacterial infection." (PMID 38594382, 2024). "Given that involvement of NK and T-cells in neurodegenerative diseases was recently proposed, the pathological roles of ISG15 mediated by NK and T-cells in SCA1 and other neurodegenerative diseases should be investigated in the future." (PMID 38594382, 2024). "Further study of the role of ISG15 and ISGylation in neurons in MS and neurodegenerative diseases is warranted." (PMID 36261842, 2022).
neurological diseases (5 papers, 2009 to 2025). "As defective protein turnover in neurons has been a hallmark of many neurological diseases, our results point to the possibility for the first time that ISG15-mediated impairment of protein degradation in A-T neurons could contribute to the progressive neurodegeneration in A-T patients." (PMID 21298066, 2011). "For example, ISG15 upregulation leads to cellular necrosis and the interruption of the blood-brain barrier, leading to neuronal damage and neurologic disorders." (PMID 40833988, 2025). "ISG15 staining in Calbindin+ Purkinje cells was greater in SCA1 patients than in non-neurological disease human controls." (PMID 38594382, 2024). "Further, UBP43 is constitutively expressed in liver, cells of the monocytic lineage and within fetal spleen, and in Ubp43−/− mice the complete lack of UBP43 expression is associated with elevated ISG15-conjugation and cellular necrosis in brain that results in severe neurological disorders." (PMID 19551150, 2009). "Finally, we summarize several ISGs (ISG15, IFIT2, IFITM3) that have been studied more in recent years for their antiviral infection in the CNS and their research progress in neurological diseases." (PMID 36325336, 2022). "In addition, substantial progress has been made in our understanding of individual ISGs (ISG15, IFIT2, IFITM3) in CNS viral infection and diseases in recent years, providing an essential target for the development of novel antivirals and anti-neurological disease drugs." (PMID 36325336, 2022).
adenocarcinoma (2 papers, 2020 to 2024). A common cancer characterized by the presence of malignant glandular cells. "The gene expression levels of hTERT, ISG15, TRF2, and POT1 were analyzed by qPCR in PC9 cells, an NSCLC adenocarcinoma cell line, and human lung fibroblast (HLF) cells." (PMID 38891017, 2024). "Consistent with RIG-I induction, cationic-lipid-mediated transfection of HCV 5′-triphosphate RNA (referred to here as “5′-ppp-RNA”) into the A549 adenocarcinoma human lung epithelial cell line resulted in the induction of both IFNB1 cytokine and ISG15 mRNA transcripts." (PMID 33184222, 2020).
cardiovascular disease (2 papers, 2020 to 2024). "Interestingly, genes in relation to cardiovascular disease such as TGFß2, Rasgrpr3 and Isg15 are subjected to significant regulation in response to both stretch and tachycardia and show a trend towards NCX dependency." (PMID 32573098, 2020).
digestive system cancer (1 paper, 2016). A primary or metastatic malignant neoplasm involving any part of the digestive system. "Limited information is available on the role of ISG15 in digestive system cancers." (PMID 27626310, 2016).
renal diseases (1 paper, 2025). "Collectively, our results demonstrate that ISG15 silencing attenuates HG‐induced TECs injury through modulation of the STING pathway, suggesting its therapeutic potential for renal diseases." (PMID 40462493, 2025).
ISG15 also shares sentences with these, for which no sentence is quoted: viral diseases (6 papers); rheumatoid arthritis (3); Cerebral ischemia (2); discoid lupus erythematosus (2); human papillomavirus infection (2); lung squamous cell carcinoma (2); multiple sclerosis (2); oligodendroglioma (2); psoriatic arthritis (2); type 1 interferonopathy (2); acute myocarditis (1); adenomyosis (1); Alzheimer disease (1); amyotrophic lateral sclerosis (1); aneurysm (1); Anorexia (1); Anxiety (1); arthrogryposis (1); astrocytoma (1); Atrophy (1); autism (1); autism spectrum disorder (1); Behçet disease (1); blood cancer (1); bovine respiratory disease complex (1); bronchitis (1); Cachexia (1); Chorioretinal atrophy (1); chorioretinitis (1); chronic kidney disease (1).
A further 75 diseases each share a sentence with ISG15 in 1 paper.